ROCK1 (Rho associated coiled-coil containing protein kinase 1)
Diseases named in the same sentence as ROCK1 in open-access papers (continued):
Sharing a sentence is not in itself a finding about the gene and the disease.
Hyperglycemia (20 papers, 2009 to 2025). An increased concentration of glucose in the blood. "Under conditions of hyperglycemia and/or hyperlipidemia, Drp1 is phosphorylated by Rho-associated protein kinase 1 (ROCK1) and extracellular signal-regulated kinase 1/2 (ERK1/2), which leads to its translocation to the OMM and the initiation of fission." (PMID 37371893, 2023). "In circulating peripheral blood and liver tissue of db/db mice, raised miR-324-5p expression was associated with hyperglycemia or hyperlipidemia leading to impaired glucose and lipid metabolism due to suppressed ROCK1 expression." (PMID 35769086, 2022). "The RhoA/ROCK1 signaling pathway is known to play an important role in endothelial cell injury caused by hyperglycemia in vitro." (PMID 29849894, 2018). "Prof. Farhad Danesh’s group demonstrated that, in diabetic kidney disease (DKD), a major disease of CKD, hyperglycemia triggers mitochondrial fragmentation mediated by the activation of Rho-associated coiled coil-containing protein kinase 1 (ROCK1) in podocytes and endothelial cells." (PMID 35163648, 2022). "Here we show, by analyzing several mutant mouse strains, that selective activation of hepatocyte G12/13 signaling leads to pronounced hyperglycemia and that this effect involves the stimulation of the ROCK1-JNK signaling cascade." (PMID 39557854, 2024). "Strikingly, the robust hyperglycemia observed with Hep-G12D mice was completely abolished in Hep-G12D ROCK1 KO mice." (PMID 39557854, 2024). "For example, hyperglycemia-induced mitochondrial fission and dysfunction in endothelial cells is mediated by activating the RhoA/ROCK1/Drp1 signaling pathway, thus contributing to vascular complications of diabetes." (PMID 35769086, 2022). "It has been reported that Rho-associated coiled coil-containing protein kinase 1 (ROCK1) activates DRP1 by phosphorylation at serine 600 residue and promoting DRP1 transfer to mitochondria in hyperglycemia-induced endothelial mitochondrial fission." (PMID 36605901, 2022). "It has reported that hyperglycemia enhances the ischemia-induced mitochondrial fission by ROCK1 activation and Drp1 translocation to the mitochondria." (PMID 34712142, 2021). "One study showed that hyperglycemia-induced mitochondrial fission depends on both ROCK1 activation and Drp1 translocation to the mitochondria." (PMID 32075676, 2020). "Simvastatin prevented high glucose or hyperglycemia-induced dysregulation of occludin and ZO-1 by inhibition of RhoA/ROCK1 signaling in cultured GEnCs and in db/db mice with early-stage DN." (PMID 24244596, 2013). "Up-regulation of ROCK1 activity has been demonstrated in the vasculature of insulin-resistant animals independently of the experimental model studied whereas hyperglycemia "per se" increases ROCK1 activity in isolated vascular cells." (PMID 19545435, 2009). "Collectively, these data indicate that S1PR2 is critical in the remodeling of mitochondrial morphology and mitochondrial functions, and may participate in hyperglycemia-induced dysfunction of HRGECs, possibly by regulating RhoA/ROCK1." (PMID 30999892, 2019). "Additionally, metformin enhanced the expression of ROCK1 under hyperglycemia-CoCl2, another moderator of cell migration." (PMID 29351188, 2018). "Hyperglycemia leads to EndMT through increased phosphorylation of ERK1/2, Angiotensin II synthesis, miR-200b and miR-328 upregulation, and ROCK1 activation." (PMID 32226439, 2020). "RhoA/ROCK1 is the key signaling pathway that couples S1PR2 and modulates endothelial cell dysfunction induced by hyperglycemia." (PMID 30999892, 2019). "Our microarray experiments demonstrated that metformin upregulated downstream targets in VEGFA pathway; MMP16, FABP4, ROCK1, TFPI2, CXCL-8, and LY96 under hyperglycemia-CoCl2, which play a part in cell migration." (PMID 29351188, 2018).
Hyperglycemia (continued). "Therefore, metformin’s dual effect in hyperglycemia-chemical hypoxia is mediated by direct effect on VEGFR1/R2 leading to activation of cell migration through MMP16 and ROCK1 upregulation, and inhibition of apoptosis by increase in phospho-ERK1/2 and FABP4, components of VEGF signaling cascades." (PMID 29351188, 2018).
cervical carcinoma (16 papers, 2015 to 2025). A carcinoma arising from either the exocervical squamous epithelium or the endocervical glandular epithelium. "DANCR can modulate the EMT progression by upregulating Rho-associated coiled-coil containing protein kinase 1 (ROCK1) and promote metastasis in cervical cancer." (PMID 31799189, 2019). "In our study, RacGAP1 could increase the level of active RhoA, which in turn caused changes in the downstream effector ROCK1 in cervical cancer." (PMID 35831303, 2022). "For instance, reduced ROCK1 expression enhances the radiation sensitivity of cervical cancer, while elevated ROCK1 expression strengthens therapeutic resistance in colitis." (PMID 40368918, 2025). "In summary, LIMK1 promotes F-actin expression and cervical cancer development by regulating the oxidative stress/src-mediated p-FAK/p-ROCK1/2/p-Cofilin-1 pathway." (PMID 38975937, 2024). "The results suggest that LIMK1 promotes the invasion, metastasis, and proliferation of cervical cancer cells and promotes cervical cancer development by regulating the oxidative stress/SRC-mediated p-FAK/p-ROCK1/2/p-Cofilin-1 pathway." (PMID 38975937, 2024). "For example, lncRNA DANCR induces cervical cancer progression by regulating the miR-335-5p/ROCK1 axis." (PMID 34271873, 2021). "OIP5-AS1 interacted with ROCK1 to promote cell carcinogenesis in cervical cancer via absorbing miR-143-3p." (PMID 33821219, 2021). "Y-27632 inhibited ROCK1 in human cervical carcinoma (CaSki) cells with overexpressed RhoC that eventually led to decreases in the rate of invasiveness and migration." (PMID 32443784, 2020). "Overexpression of tumor suppressor miR-217 reduced colony formation and cell invasion and significantly increased apoptosis in cervical cancer (SiHa, HeLa) cells through ROCK-1 targeting." (PMID 32443784, 2020). "Previous studies have shown that the expression of RhoA, ROCK-1, and ROCK-2 is significantly elevated in cervical cancer cells." (PMID 40655948, 2025). "And through the correlation analysis of the expressions of ECT2 and RHOA, ROCK1, and ROCK2 in cervical cancer samples in TCGA database, it was found that the expression of ECT2 was significantly positively correlated with RhoA, ROCK1, and ROCK2." (PMID 40655948, 2025). "In conclusion, our study reveals the mechanism of action of LIMK1 in cervical cancer progression, suggesting that LIMK1 can promote the development of cervical cancer by regulating the oxidative stress/Src-mediated p-FAK/p-ROCK1/2/p-Cofilin-1 pathway." (PMID 38975937, 2024). "In cervical cancer, OIP5-AS1 and DANCR were found to up-regulate ROCK1 via sponging miR-143-3p and miR‐335‐5p, respectively." (PMID 36177350, 2022). "Our study demonstrated ROCK1 was adownstream effector of OIP5-AS1 in the regulation of cervical cancer, and thus theOIP5-AS1-ROCK1 pathway was identified." (PMID 31939597, 2020).
pancreatic cancer (16 papers, 2011 to 2025). "ROCK1, a member of the Rho-associated coiled-coil protein kinases (ROCKs), plays a key role in pancreatic cancer metastasis and progression." (PMID 40630951, 2025). "The Cancer Genome Atlas (TCGA) data analysis revealed that NT5E gene expression was strongly correlated with CD44 and ROCK1/ROCK2 gene expressions in pancreatic tumors, suggesting a link between CD73 and loss of epithelial features." (PMID 37851808, 2023). "Though endothelial nitric oxide synthase (eNOS) and the PI3K/Akt pathway appear to be implicated in ROCK signaling in cardiac models, ROCK1 in pancreatic cancer or CAFs specifically is less well understood." (PMID 28841710, 2017). "Knockdown of ROCK1 can effectively inhibit pancreatic cancer growth in vivo and increase tumor sensitivity to gemcitabine, providing a new strategy for clinical treatment." (PMID 40630951, 2025). "In a recent research, LINC00941 was shown to enhance pancreatic cancer growth by competing with miR-335-5p to inhibit the ROCK1-mediated LIMK1/cofilin-1 signaling pathway." (PMID 34764994, 2021). "Overexpression of miR-146a inhibits the proliferation and survival of breast, prostate, and pancreatic cancer cells through the downregulation of its targets including ROCK1, EGFR, and MTA-2." (PMID 28435518, 2017). "Elevated ROCK1 and/or ROCK2 expression was associated with shorter survival in human pancreatic cancer patients, while conditional ROCK activation in KrasG12D‐driven PDAC mice was sufficient to accelerate mortality." (PMID 28031255, 2017). "We first compared the expression of ROCK1 among multiple, established pancreatic cancer cell lines, as well as the immortalized normal pancreatic ductal epithelial cell line HPDE6 and the CAF cells (CW-1) isolated from a PDAC patient’s tumor." (PMID 28841710, 2017). "ROCK1 stimulates the growth and metastasis of pancreatic cancer (PC) cells and ROCK1 may therefore represent potential targets for clinical PC treatment." (PMID 36197602, 2022). "Furthermore, HIF-3α has been implicated in the progression of pancreatic cancer by directly binding the promoters of RHOC and ROCK1 and transactivating the RhoC-ROCK1 pathway in cancer cells that overexpress HIF3A." (PMID 31768607, 2020). "In the current study, we investigated the hypothesis that ROCK1 plays a role in physiological chemoresistance and mediates the reduced efficacy of chemotherapeutics in pancreatic cancer." (PMID 28841710, 2017). "Overall, our data suggests that ROCK1 may serve as a potential therapeutic target to enhance current treatment regimens for pancreatic cancer." (PMID 28841710, 2017). "Furthermore, TCGA Research Network data also revealed significantly coordinated ROCK1 and ROCK2 mRNA expression in pancreatic cancers, consistent with an observed advantage associated with increased ROCK signaling in pancreatic cancer." (PMID 28031255, 2017). "Altered ROCK1 expression has been shown in breast tumors, osteosarcoma, and pancreatic cancer." (PMID 28841710, 2017). "Activation of ROCK1 or ROCK2 signalling induced significant changes in gene expression that could be used to determine how actomyosin contractility influences gene transcription in pancreatic cancer." (PMID 27824338, 2016). "This might be due to the fact that ROCK1 expression is already abundant in pancreatic cancer cells." (PMID 21722395, 2011). "ROCK1 promotes, through the c-Myc/PFKFB3 signaling pathway, the glycolysis in pancreatic cancer cells and drives tumor growth." (PMID 40630951, 2025). "ROCK1 protein was also detected in 18 of 21 pancreatic cancer samples and five cell lines, but not in 10 normal pancreas specimens." (PMID 28031255, 2017). "However, the potential for ROCK1 inhibition to enhance chemotherapeutic regimens has not been investigated in a proper model which recapitulates the pancreatic tumor microenvironment." (PMID 28841710, 2017).
pancreatic cancer (continued). "In addition, the expression of ROCK1 is almost always found in pancreatic cancer tissues, but not in normal pancreatic tissues." (PMID 21722395, 2011).
colon cancer (15 papers, 2016 to 2023). "They include upregulation of RhoA and ROCK1 expression, acquiring activating mutations of ROCK1 in microsatellite-instable colon cancer, as well as frequent inactivating mutations of upstream negative regulators of RhoA, Rho GTPase-activating proteins." (PMID 33670106, 2021). "Consistently, the transwell assay results revealed that circCSPP1 notably promoted the migration and invasion of colon cancer cells, whereas these effects were reversed by miR-431 mimics or ROCK1 knockdown." (PMID 35101080, 2022). "In this study, we affirmed that miR-148a indirectly inhibited the expression of HIF-1α and Mcl-1 by directly binding to ROCK1 and c-Met, thereby enhancing apoptosis of colon cancer cells and decreasing angiogenesis in tissues containing such cells." (PMID 35997665, 2022). "We confirmed that miR-148a directly targeted the 3′-UTR of ROCK1 and c-Met in colon cancer cell lines in the current study." (PMID 35997665, 2022). "In this current study, we supposed that miR-148a directly targets ROCK1 and c-Met to decrease angiogenesis and increase the apoptosis of colon cancer cells by inhibiting the secretion of VEGF and Mcl-1 through downregulation of HIF-1α under hypoxia." (PMID 35997665, 2022). "RT-qPCR results revealed that ROCK1 expression was notably upregulated in colon cancer tissues compared with adjacent normal tissues." (PMID 35101080, 2022). "Similar to these reports, the present study found that circCSPP1 promoted the progression of colon cancer by sponging a new microRNA miR-431 and regulating the expression of ROCK1 and ZEB1." (PMID 35101080, 2022). "The actin depolymerization pathway has been recognized as a critical cellular response that controls the apoptosis and inhibition of cell migration triggered in prostate, breast and colon cancer cells through ROCK1/LIMK2/Cofilin cascades." (PMID 27709782, 2017). "In addition, miR-148a can directly target ROCK1/c-Met to inhibit Mcl-1 protein expression, thereby reducing angiogenesis and increasing apoptosis in colon cancer cells." (PMID 37259388, 2023). "On the whole, these data confirmed that ROCK1 was a target gene of miR-431 in colon cancer cells." (PMID 35101080, 2022). "Taken together, the findings of the present study indicated that circCSPP1 may function as a competing endogenous RNA in the progression of colon cancer by regulating the miR-431/ROCK1 and miR-431/ZEB1 signaling axes." (PMID 35101080, 2022). "The role of ROCK1 in the regulation of the cell cycle may explain its effect on the proliferation of colon cancer cells." (PMID 35101080, 2022). "In addition, circCSPP1 promoted the progression of colon cancer functions as a competing endogenous RNA by the regulating miR-431/ROCK1 and miR-431/ZEB1 pathways." (PMID 35101080, 2022). "In addition, the results of CCK-8 and colony formation assays indicated that circCSPP1 significantly increased the proliferation of colon cancer cells, which was reversed by transfection with miR-431 mimics or ROCK1 knockdown." (PMID 35101080, 2022). "One of the main findings of the current study is that miR-148a could decrease angiogenesis in and increase the apoptosis of colon cancer cells via direct downregulation of ROCK1 and c-Met and their relevant pathways." (PMID 35997665, 2022). "Finally, our research demonstrated that miR-148a downregulated HIF-1α/VEGF and Mcl-1 by directly targeting ROCK1/c-Met to decrease angiogenesis and increase the apoptosis of colon cancer cells." (PMID 35997665, 2022). "Interestingly, ROCK1 expression is higher in leukemia and lymphoma cell lines, compared to other types of cancer cell lines, whereas ROCK2 expression is the highest in colon cancer cells." (PMID 35365653, 2022).
Insulin resistance (15 papers, 2009 to 2025). Increased resistance towards insulin, that is, diminished effectiveness of insulin in reducing blood glucose levels. "On the other hand, ROCK1 was shown to be required for insulin-induced GLUT4 translocation in cultured cells, and targeted knockout of ROCK1 caused whole body insulin resistance in mice." (PMID 24466133, 2014). "Pharmacologically, a novel small molecule kinase inhibitor of ROCK1/2 that preferentially accumulated in liver tissue ameliorated insulin resistance and decreased liver injury, inflammation, and fibrosis in mice fed the FFC NASH diet." (PMID 39779619, 2025). "Elevated ROCK1 activity contributes to insulin resistance, and its inhibition, as seen in our treatment groups, has been shown to improve insulin sensitivity and directly promote GLUT4 translocation in insulin-responsive tissues." (PMID 40954151, 2025). "ROCK1 is increased in human fatty liver diseases, and overexpression of ROCK1 in the liver promotes adiposity, insulin resistance and lipid accumulation in mice with a high-fat diet." (PMID 40182055, 2025). "During period of physical inactivity, the increased skeletal muscle miR-148b expression triggered the downregulation of ROCK1 expression and insulin resistance in humans and mice." (PMID 35769086, 2022). "Although these studies established a role for hepatic ROCK1 in promoting adiposity, insulin resistance, and hepatic lipid accumulation, the role for hepatic ROCK2 in regulating these metabolic functions remains to be explored." (PMID 35769086, 2022). "In mice, global ROCK1-deletion triggers whole body insulin resistance by impairing skeletal muscle insulin signaling." (PMID 34443331, 2021). "The kinome analysis of T2D iHeps also predicted the kinases responsible for emergent signaling that may act as drivers of insulin resistance, including ROCK1/2, BCKDK, and MST4 for insulin-regulated phosphorylations." (PMID 40231468, 2025). "Treatment with ROCK inhibitors and genetic ablation of ROCK1 have also been shown to ameliorate inflammation and fibrosis in rodent models of NASH, as well as hepatic steatosis and insulin resistance." (PMID 40231468, 2025). "On the other hand, ROCK1/AMPK/SREBP1c and ROCK/IRS1 pathways have been found involved in lipotoxicity and insulin resistance on HFD." (PMID 35769086, 2022).